ALDH2 (aldehyde dehydrogenase 2 family member)
Diseases named in the same sentence as ALDH2 in open-access papers (continued):
Sharing a sentence is not in itself a finding about the gene and the disease.
Hypertension (continued). "Thirdly, other genetic variations in ALDH2 and MTHFR genes may influence the development of hypertension in this population." (PMID 35346052, 2022). "Studies have indicated that ALDH2 plays a protective role through the detoxification and clearance of 4-HNE in various oxidative stress-mediated cardiopulmonary diseases, such as myocardial ischemia/reperfusion, hypertension, and myocardial infarction." (PMID 35770049, 2022). "In our previous study, the proteomic response that contributes to the SHR phenotype and reduction of hypertension in LR3-needled rats includes the modulation of seven proteins related to oxidative stress in the medulla oblongata, including SOD, ALDH2, GSTM5, GLUD1, protein DJ-1, Hsp90a, and a-ETF." (PMID 29853959, 2018). "In conclusion, our results provides evidence that the ALDH2 rs671 L-genotypes are protective factors for hypertension in Han Chinese, independent of alcohol consumption and sex." (PMID 28894224, 2017). "In vivo, MAOA was induced during aging and hypertension but the expression of the corresponding serotonin uptake receptor (SLC6A4) was reduced and enzymes that reduce either oxidative stress (CAT) or accumulation of 5-hydroxyindolacetaldehyde (ALDH2) were induced." (PMID 37371593, 2023). "Therefore, ALDH2 is highly likely to have a male-specific genetic effect on the development of hypertension, even though the SNP was not significant in the heterogeneity test." (PMID 34828409, 2021). "Moreover, hypertension prevalence was lower in ALDH2 *2 carriers than that in ALDH2 *1/*1 carriers in drinkers, but not in nondrinkers, in a Chinese population." (PMID 26599441, 2015). "As a result, in GWAS of high blood pressure, ALDH2 was not identified in studies that recruited predominantly European samples but was identified in studies that recruited East Asian samples (once genotyping chips that adequately tagged the ALDH2 locus were used)." (PMID 26866486, 2016). "The mean values of BMI, BP and the levels of transaminases and the prevalence of hypertension were significantly higher in the subjects with a high GGT level than in those with a low GGT level, irrespective of the ALDH2 genotype." (PMID 24028448, 2013).
diabetes (65 papers, 2010 to 2026). "It has been widely recognized that ALDH2 polymorphism influences the development of various health impairments, including cardiovascular disease, diabetes mellitus, cancer, liver disease, and neurodegenerative disorder." (PMID 41542286, 2026). "Similar to previous studies, the ALDH2–diabetes association was only significant in male participants." (PMID 40046877, 2025). "Stratified analyses examining the association between the ALDH2 genotype and diabetes risk across different population subgroups in male participants." (PMID 40046877, 2025). "Our previous meta-analysis of 46 studies with over 90,000 participants revealed heterogeneous associations between ALDH2 variants and diabetes risk." (PMID 40046877, 2025). "The meta-analysis demonstrated that the ALDH2 rs671 G allele increases diabetes risk, suggesting a potential protective effect of the A allele." (PMID 40046877, 2025). "Both BMI (p = 0.037) and WC (p = 0.024) modified the association between the ALDH2 genotype and diabetes risk." (PMID 40046877, 2025). "Multivariable analyses of associations between the ALDH2 rs671 genotype and diabetes-related outcomes in male participants." (PMID 40046877, 2025). "Although our findings of ALDH2's effects on diabetes risk through adiposity measures are supported by molecular studies and imaging evidence, future research would be valuable to further elucidate the underlying mechanisms." (PMID 40046877, 2025). "We also investigated the extent to which alcohol consumption and other factors mediate or modify the relationship between ALDH2 rs671 polymorphism and diabetes." (PMID 40046877, 2025). "We evaluated the association between ALDH2 rs671 and diabetes risk using both logistic and Cox regression models, with age as the time scale and adjustment for potential confounders." (PMID 40046877, 2025). "Mediation analysis, adjusted for potential confounders, revealed that anthropometric measures partially mediated the association between ALDH2 rs671 and diabetes risk." (PMID 40046877, 2025). "Conversely, ALDH2 deficiency in these mice exacerbated these conditions, demonstrating its protective role against mitochondrial dysfunction in diabetes." (PMID 40564981, 2025). "While several Mendelian randomization studies have confirmed both the association between ALDH2 rs671 and alcohol consumption and the causal relationship between alcohol intake and diabetes development, evidence directly linking these factors remains limited." (PMID 40046877, 2025). "In a recent report, the accumulation of 4-HNE and excessive mitofission were noted in cardiomyocytes from mice with streptozotocin-induced diabetes, along with evident apoptosis, which was caused by the defective activation of ALDH2." (PMID 40968356, 2025). "A landmark meta-analysis of 433,540 East Asian individuals provided robust evidence for several previously unreported diabetes-associated variants, with aldehyde dehydrogenase-2 (ALDH2) rs671 emerging as particularly noteworthy." (PMID 40046877, 2025). "ALDH2 polymorphism was statistically reported with Type 2 diabetes mellitus among Japanese population and with a rise in insulin resistance (estimated by HOMA-IR levels)." (PMID 39905472, 2025). "In this community-based study, male carriers of the ALDH2 rs671 GG genotype demonstrated increased diabetes susceptibility compared to GA/AA carriers." (PMID 40046877, 2025). "The cardiovascular implications of ALDH2 deficiency are profound, particularly in individuals with diabetes, as the impaired detoxification of toxic aldehydes, such as acetaldehyde and 4-HNE, exacerbates oxidative stress and inflammation." (PMID 40564981, 2025). "The association between the ALDH2 rs671 A allele count and diabetes risk consistently supported these findings." (PMID 40046877, 2025). "Given the increasing prevalence of diabetes in these regions, ALDH2*2 carriers are at compounded risk, underscoring the urgent need for targeted interventions." (PMID 40564981, 2025).
diabetes (continued). "Diabetic cardiomyopathy (DCM) is a significant complication of diabetes, particularly affecting East Asian populations with a high prevalence of the ALDH2*2 (Glu504Lys) genetic variant." (PMID 40564981, 2025). "Among male participants, the ALDH2 rs671 GA/AA genotype was associated with a lower diabetes risk compared to the GG genotype after adjusting for alcohol consumption and other potential confounders (OR = 0.751, 95% CI: 0.567–0.995)." (PMID 40046877, 2025). "This study aimed to examine the ALDH2–diabetes association using standardized clinical criteria while systematically investigating potential confounding, mediating, and interacting factors in a community-based cohort." (PMID 40046877, 2025). "A study with diabetic-induced ALDH2 knockout mice showed that ALDH2 deficiency increases diabetes-induced oxidative stress by increasing the lipid peroxidation product, 4-hydroxynonenal." (PMID 39075523, 2024). "Numerous studies have confirmed that ALDH2 mutation plays a critical role in alcohol use disorders, cancer, cardiovascular diseases, diabetes mellitus, and neurodegenerative diseases." (PMID 36670098, 2023). "We found a significant increase in myocardial 8-OHdG, an index of oxidative DNA damage, in vehicle-treated ALDH2*2 mice with diabetes-associated HFpEF in relation to control." (PMID 36142350, 2022). "EMP + Alda-1 improved exercise tolerance, diastolic and systolic function, 4HNE detoxification and cardiac liver kinase B1 (LKB1)-AMP-activated protein kinase (AMPK) pathways in ALDH2*2 mice with diabetes-associated HFpEF." (PMID 36142350, 2022). "In fact, a recent clinical study in East Asians with the ALDH2*2 mutation demonstrated an association between ALDH2*2 and HFpEF in patients who have diabetes and other comorbidities." (PMID 36142350, 2022). "Among ISR patients with diabetes, 27 (55.1%) carried the ALDH2*1/*1, 20 (40.8%) carried the ALDH2*1/*2 allele, and 2 (4.1%) carried the ALDH2*2/*2 allele." (PMID 31345174, 2019). "The SNP rs671 in ALDH2 was reported to be associated with metabolic traits, including diabetes mellitus, and blood pressure." (PMID 29558500, 2018). "In the present study, among G allele carriers, the diabetes duration and ALDH2*2 allele were other independent risk factors for DR." (PMID 25952030, 2015). "This study is the first to investigate the association of genetically determined ALDH2 activity and diabetic complications in relation to alcohol consumption in a large population of patients with type 2 diabetes mellitus." (PMID 26599441, 2015). "Using a genetic variant in the ALDH2 gene associated with alcohol consumption, rs671, we performed a Mendelian randomization analysis in 1,712 diabetes cases and 2,076 controls from Nantong, China." (PMID 26364564, 2015). "Among the ALDH2*2 allele carriers, the duration of diabetes was also added to the risk factors (HR: 1.11; P = 0.01) and a high GGT level appeared to be a potential risk factor (HR: 1.91; P = 0.14) for DR." (PMID 24028448, 2013). "In mediation analysis, abdominal adiposity accounted for 30.4% (95% CI: 10.0%–127.0%) of the ALDH2–diabetes association and BMI mediated 18.9% (95% CI: 4.8%–75.4%) of this relationship, while alcohol consumption showed no significant mediating effect (p = 0.56)." (PMID 40046877, 2025). "Instead, our analysis revealed that approximately 30% of the diabetes risk reduction could be attributed to the effect of ALDH2 rs671 on WC." (PMID 40046877, 2025). "The exact mechanism linking ALDH2 rs671 polymorphism to diabetes risk has been debated." (PMID 40046877, 2025). "The ALDH2*2 variant is linked to multiple mechanisms—such as altered alcohol metabolism, oxidative stress, and inflammation—that exacerbate traditional cardiovascular risk factors, such as high blood pressure and diabetes." (PMID 40564981, 2025).
diabetes (continued). "This raises important questions about whether the association between ALDH2 variants and diabetes is primarily mediated through alcohol consumption or alternative pathways." (PMID 40046877, 2025). "Also, Aldehyde dehydrogenase 2 (ALDH2) polymorphism has been reported as a risk factor for type 2 diabetes mellitus (T2DM) and is associated with liver insulin resistance." (PMID 39905472, 2025). "The association between aldehyde dehydrogenase-2 (ALDH2) rs671 and diabetes remains controversial, with uncertainty about whether alcohol consumption or other factors mediate or modify this relationship." (PMID 40046877, 2025). "A quantitative umbrella review will be conducted on meta-analyses of genetic association studies to examine the pleiotropic effects of ALDH2 rs671, mainly including cardio-cerebral vascular disease, diabetes mellitus, cancer, neurodegenerative disease, and alcohol-induced medical disease." (PMID 36050775, 2022). "East Asians with the ALDH2*2 mutation have a higher incidence of cardiovascular and metabolic diseases, such as diabetes, diabetes-induced neuropathy and vasculopathy and diabetes-induced diastolic dysfunction." (PMID 36142350, 2022). "Our data indicate that ALDH2 activation along with the treatment of hypoglycemic agents may be a salient strategy to alleviate diabetes-associated HFpEF." (PMID 36142350, 2022). "In addition, some reports have suggested that the ALDH2-deficient variant allele contributes to cardiovascular disease, diabetes, stroke, and cancer." (PMID 36340257, 2022). "However, another study in a Chinese population using the ALDH2 rs671 variant, which has a more profound effect on alcohol intake, found a higher risk of diabetes with increasing alcohol." (PMID 34379647, 2021). "The ADH1B and ALDH2 gene polymorphisms in Japanese alcoholics modify cardiovascular risk factors such as weight gain, hypertension, and diabetes mellitus; therefore, these polymorphisms may play an indirect role in the development of cardiovascular diseases." (PMID 26284938, 2015). "The present study suggests that ALDH2 deficiency as a result of the ALDH2 *2 allele may be a risk factor for brain infarction development in Japanese patients with type 2 diabetes mellitus." (PMID 26599441, 2015). "Collectively, clinical studies have illustrated that individuals with the ALDH2*2 variant have a heightened risk of cardiovascular and metabolic complications—especially in East Asian populations with high variant prevalence—and this risk is exacerbated by alcohol consumption and diabetes." (PMID 40564981, 2025). "Molecular studies have identified ALDH2's direct biological role in adipocyte differentiation and adipogenesis, which may represent the potential mechanism through which ALDH2 influences diabetes risk by regulating both fat accumulation (BMI) and ectopic fat distribution (WC)." (PMID 40046877, 2025). "In addition, diabetic retinopathy development may be associated with the ALDH2 SNP in Japanese patients with type 2 diabetes mellitus." (PMID 26599441, 2015). "ALDH2 is an important limiting factor for diabetes, and its deletion significantly exacerbates pancreatic beta cell apoptosis in response to glucolipotoxicity." (PMID 40968356, 2025). "As the burden of diabetes continues to rise globally, particularly in East Asian regions with high ALDH2*2 prevalence, restoring ALDH2 function represents a promising precision medicine strategy for mitigating DCM and related cardiometabolic complications." (PMID 40564981, 2025). "The sex-specific effects observed in our study can be explained by our mediation analysis findings that abdominal adiposity significantly mediates the ALDH2–diabetes relationship." (PMID 40046877, 2025). "mtDNA variants linking diabetes studied mostly in CRIF1 Deficiency in Mice, Cdk5 Expression in Diabetic Nephropathy, ALDH2*2 Mutant Mice, Mitochondrial Cardiomyopathy in Mice." (PMID 39835172, 2025).
diabetes (continued). "Our findings highlight the potential value of considering ALDH2 genotype status when developing personalized diabetes prevention strategies, particularly in East Asian populations." (PMID 40046877, 2025). "This study shows that combined treatment with EMP, a SGLT2 inhibitor that lowers hyperglycemia and Alda-1, an ALDH2 activator, improved exercise tolerance and diastolic function better than EMP alone in a mouse model of HFpEF associated with diabetes." (PMID 36142350, 2022). "Most importantly, diabetes was shown to decrease ALDH2 activity in non-ALDH2*2 mutant animals i.e., WT animals as well." (PMID 36142350, 2022). "In this animal model of diabetes, it has also been confirmed that in the course of diabetes, an important, mitochondrial antioxidant enzyme, aldehyde dehydrogenase (ALDH-2) is inactivated." (PMID 33150520, 2021). "Recently, ALDH2 has gained increasing attention for providing endogenous protection against several human diseases, including cardiovascular dysfunction, diabetes mellitus and neurodegenerative disorders." (PMID 32070320, 2020). "ALDH2 and its agonist Alda-1 are likely to offer protection by reversing diabetes or significant glucose-induced changes in AMPK and FOXO3a signaling, en route to improved autophagy, cardiac geometry, and mechanical function." (PMID 32325880, 2020). "ALDH2 overexpression or its agonist Alda-1 improved autophagy to reverse diabetes or high glucose-induced dysfunctions via AMPK and forkhead box O3a (FOXO3a)." (PMID 32116717, 2020). "Previous studies had shown that ALDH2 attenuated diabetes-induced myocardial injury, but is ALDH2 expressed in cardiac fibroblasts?" (PMID 29129988, 2017). "ALDH2 has the protective effects on the various types of cardiovascular injury, such as microvascular injury induced by diabetes, myocardial injury in diabetic rats, and cardiomyocyte injury induced by high glucose." (PMID 29129988, 2017). "Our previous studies had reported that increasing ALDH2 expression can ameliorate myocardial ischemia/reperfusion injury and diabetes mellitus-induced myocardial injury." (PMID 29129988, 2017). "It is suggested that the expression of ALDH2 was related to the cardiac I/R injury induced by diabetes." (PMID 27829984, 2016). "In summary, our results demonstrate that with the progression of diabetes, ALDH2 expression was decreased accompanied with the happening of myocardium fibrosis." (PMID 27547765, 2016). "Many studies have demonstrated that ALDH2 overexpression or activation alleviates myocardial injury induced by I/R diabetes, doxorubicin, acetaldehyde, and alcohol." (PMID 27148058, 2016). "Our previous observation points out that long-term diabetes in patients reduces ALDH2 activity and increases 4HNE adduct formation in diabetic hearts." (PMID 27882330, 2016). "It has been shown that ALDH2 activity and levels were decreased in streptozotocin-induced diabetes in rats and mice." (PMID 27736868, 2016). "The result showed that ALDH2 overexpression reconciled diabetes-induced contractile dysfunction, whereas cardioprotection elicited by ALDH2 was blocked by the inhibitor CYA." (PMID 27829984, 2016). "Earlier findings from our group also indicated that activation of ALDH2 with ethanol attenuated diabetes-induced myocardial injury in rats." (PMID 27829984, 2016). "The role of ALDH2 or aldehydes in the pathogenesis of diabetes and obesity has not been fully understood." (PMID 27575855, 2016). "Our previous results had indicated that ALDH2 expression was further decreased accompanying the development of diabetes." (PMID 27547765, 2016). "The aim of this paper is to observe the change of mitochondrial aldehyde dehydrogenase 2 (ALDH2) when diabetes mellitus (DM) rat heart was subjected to ischemia/reperfusion (I/R) intervention and analyze its underlying mechanisms." (PMID 27829984, 2016).